DNAJC9 (DnaJ heat shock protein family (Hsp40) member C9)
Description:
Acts as a dual histone chaperone and heat shock co-chaperone. As a histone chaperone, forms a co-chaperone complex with MCM2 and histone H3-H4 heterodimers; and may thereby assist MCM2 in histone H3-H4 heterodimer recognition and facilitate the assembly of histones into nucleosomes. May also act as a histone co-chaperone together with TONSL. May recruit histone chaperones ASF1A, NASP and SPT2 to histone H3-H4 heterodimers. Also plays a role as co-chaperone of the HSP70 family of molecular chaperone proteins, such as HSPA1A, HSPA1B and HSPA8. As a co-chaperone, may play a role in the recruitment of HSP70-type molecular chaperone machinery to histone H3-H4 substrates, thereby maintaining the histone structural integrity. Exhibits activity to assemble histones onto DNA in vitro.
Synonyms: HDJC9; JDD1; SB73
Tractability: Antibody: UniProt places it where antibodies can reach, with high confidence; its Gene Ontology location is reachable by antibodies, with high confidence; the Human Protein Atlas places it where antibodies can reach. PROTAC: ubiquitination databases record sites on it; its protein half-life has been measured.
Gene: Protein-coding gene on chromosome 10 (73,183,362 to 73,247,280, reverse strand). Ensembl gene ENSG00000213551.
Subcellular location: Nucleus; Cytoplasm; Cell membrane
Subcellular location (Human Protein Atlas): Nucleoplasm; Cytosol; Plasma membrane
Gene Ontology:
Molecular function: heat shock protein binding; histone binding; protein binding; protein-folding chaperone binding
Biological process: nucleosome assembly; positive regulation of ATP-dependent activity
Cellular component: cytoplasm; cytosol; extracellular region; nucleoplasm; nucleus; plasma membrane; protein folding chaperone complex
Genetic constraint (gnomAD): Loss-of-function variants: 18 observed, 31.7 expected, observed/expected ratio (o/e) 0.57, 90% interval 0.39 to 0.84. The upper end of that interval is the gene's LOEUF score, 0.84, which puts it in group 3 of 6, group 1 being the genes least tolerant of losing a copy. Missense variants: 310 observed, 309.06 expected, observed/expected ratio (o/e) 1, 90% interval 0.91 to 1.1. Synonymous variants: 113 observed, 113.16 expected, observed/expected ratio (o/e) 1, 90% interval 0.86 to 1.17.
Homologues: Orthologues: chimpanzee DNAJC9 (98% identical), pig DNAJC9 (94% identical), dog DNAJC9 (93% identical), guinea pig DNAJC9 (92% identical), mouse Dnajc9 (88% identical), rat Dnajc9 (78% identical), macaque DNAJC9 (77% identical), zebrafish dnajc9 (57% identical), Drosophila melanogaster CG6693 (39% identical), Caenorhabditis elegans dnj-2 (14% identical), Caenorhabditis elegans dnj-7 (10% identical), Caenorhabditis elegans dnj-28 (8% identical), and 1 more. Paralogues in human: DNAJC16 (25% identical), DNAJC13 (23% identical), DNAJC21 (20% identical), DNAJC1 (18% identical), DNAJC10 (18% identical), DNAJC18 (17% identical), DNAJC11 (17% identical), DNAJC2 (16% identical), DNAJC25 (16% identical), DNAJC4 (14% identical), DNAJC7 (14% identical), DNAJC17 (13% identical), and 8 more.
Diseases named in the same sentence as DNAJC9 in open-access papers:
DNAJC9 is named in the same sentence as 13 diseases in open-access papers, as found by Europe PMC text mining. Sharing a sentence is not in itself a finding about the gene and the disease. The quoted sentences say what the papers report.
bladder urothelial carcinoma (1 paper, 2020). "For example, DNAJC9 was upregulated in 8 cancer types, including bladder urothelial carcinoma (BLCA), stomach adenocarcinoma (STAD), and lung squamous cell carcinoma (LUSC), while DNAJC27 was downregulated in 9 cancer types, including LUAD, kidney renal clear cell carcinoma (KIRC) and BRCA." (PMID 33225964, 2020).
breast carcinoma (1 paper, 2024). "The expressions of DNAJA1 and DNAJC9 genes were elevated in breast cancer samples and BCSCs, which is considered unfavorable for survival in breast cancer." (PMID 38255948, 2024).
cervical cancer (1 paper, 2017). A primary or metastatic malignant neoplasm involving the cervix. "These genes were also shown to be dysregulated in cancer: C9orf40 was reported to be dysregulated in ovarian carcinoma whereas DNAJC9 was shown to be up-regulated in metastatic cervical cancer in cancer stem cells." (PMID 28056781, 2017).
COVID-19 (1 paper, 2025). A disease caused by infection with severe acute respiratory syndrome coronavirus 2. "Our analysis revealed increased plasma levels of DNAJC9, DNAJC17, and DNAJA4 in PLWH diagnosed with COVID-19, though these elevations were not statistically significant after FDR adjustment." (PMID 40568587, 2025).
glioblastoma (1 paper, 2021). The most malignant astrocytic tumor (WHO grade IV). "Other members have been implicated in cancer development and metastasis, such as DNAJA1 (in glioblastoma and prostate), DNAJB11 (in ovarian tumors), and DNAJC9 (cervical)." (PMID 33810095, 2021).
lung carcinoma (1 paper, 2020). "We experimentally characterized the dual function of two genes, DNAJC9 and HSPA14, in lung cancer cells." (PMID 33225964, 2020). "Among these, we experimentally validated the dual functions of DNAJC9 and HSPA14 in a lung cancer cell line." (PMID 33225964, 2020).
marginal zone lymphoma (1 paper, 2022). A usually indolent mature B-cell lymphoma, arising from the marginal zone of lymphoid tissues. "Immunohistochemistry and immunofluorescent staining showed the nuclear staining of DNAJC9 was significantly higher in extranodal marginal zone lymphomas compared with inflammation specimens." (PMID 35906682, 2022).
cancer (8 papers, 2017 to 2025). A tumor composed of atypical neoplastic, often pleomorphic cells that invade other tissues. "While Djc9 is dispensable for cell viability in fission yeast, the DepMap database indicates that DNAJC9 is essential for cell viability in the majority of cancer cell lines." (PMID 39878217, 2025). "In providing this function, we demonstrate that DNAJC9 prevents the promiscuous entry of CENP-A into H3–H4 deposition pathways to prevent CIN, which is a known hallmark of many cancers." (PMID 38600242, 2024). "Previous studies have demonstrated roles for the histone chaperones such as HIRA, CHAF1B and the molecular co-chaperone DNAJC9 in preventing CENP-A mislocalization in human cancer cells lines." (PMID 39135477, 2024). "For example, DNAJC9 promoted cell proliferation while inhibiting EMT in 18 cancer types, including BLCA, LUAD, and STAD." (PMID 33225964, 2020). "For example, knockout of HSPE1, HSPA9, and DNAJC9 significantly reduced cell proliferation across 21 cancer cell lineages." (PMID 33225964, 2020). "However, how DNAJC9 contributes to cancer progression remains to be elucidated." (PMID 34948322, 2021). "Among these HSPs, DNAJC9 and HSPA14 are two top genes with striking dual functions in that they promoted cell proliferation but inhibited EMT in 18 and 17 cancer types, respectively (i.e., in LUAD)." (PMID 33225964, 2020). "For example, DNAJC9 positively correlated with cell proliferation in 32 cancer types, and HSPA14 positively correlated with cell proliferation in 24 cancer types." (PMID 33225964, 2020). "For example, in HSP40 families, DNAJC9 positively correlated with cell proliferation across all cancer cell lines and 14 cancer lineages, while DNAJB9 negatively correlated with cell proliferation across all cancer cell lines, as well as 13 cancer lineages." (PMID 33225964, 2020).
tumor (4 papers, 2021 to 2025). "Both TPR and DNAJC9 might have dual function in term of tumour biology." (PMID 36420261, 2022).
DNAJC9 also shares sentences with these, for which no sentence is quoted: lung squamous cell carcinoma (1 paper); ovarian carcinoma (1); ovarian tumors (1); stomach adenocarcinoma (1).